NPFFR2 (neuropeptide FF receptor 2)
Description:
Receptor for NPAF (A-18-F-amide) and NPFF (F-8-F-amide) neuropeptides, also known as morphine-modulating peptides. Can also be activated by a variety of naturally occurring or synthetic FMRF-amide like ligands. This receptor mediates its action by association with G proteins that activate a phosphatidylinositol-calcium second messenger system.
Synonyms: GPR74; NPFF2; NPGPR; HLWAR77
Tractability: Small molecule: a high-quality ligand is known; it belongs to a druggable protein family. Antibody: UniProt places it where antibodies can reach, with high confidence; its Gene Ontology location is reachable by antibodies, with high confidence; UniProt predicts a signal peptide or a membrane-spanning region. PROTAC: a small molecule that binds it is known.
Target class: Membrane receptor; RF amide receptor; Family A G protein-coupled receptor; Peptide receptor (family A GPCR); Short peptide receptor (family A GPCR)
Gene: Protein-coding gene on chromosome 4 (72,031,902 to 72,148,311, forward strand). Ensembl gene ENSG00000056291.
Subcellular location: Cell membrane
Subcellular location (Human Protein Atlas): Plasma membrane; Actin filaments
Pathways (Reactome):
Signal Transduction: G alpha (q) signalling events; Orexin and neuropeptides FF and QRFP bind to their respective receptors
Gene Ontology:
Molecular function: neuropeptide receptor activity; protein binding; G protein-coupled receptor activity; opioid receptor binding
Biological process: neuropeptide signaling pathway; cellular response to hormone stimulus; detection of abiotic stimulus; G protein-coupled receptor signaling pathway; regulation of MAPK cascade
Cellular component: plasma membrane; membrane
Genetic constraint (gnomAD): Loss-of-function variants: 6 observed, 7.24 expected, observed/expected ratio (o/e) 0.83, 90% interval 0.45 to 1.59. That is too few expected variants to judge how well the gene tolerates losing a copy. Missense variants: 544 observed, 506.01 expected, observed/expected ratio (o/e) 1.08, 90% interval 1 to 1.15. Synonymous variants: 184 observed, 181.79 expected, observed/expected ratio (o/e) 1.01, 90% interval 0.9 to 1.14.
Homologues: Orthologues: chimpanzee NPFFR2 (99% identical), macaque NPFFR2 (95% identical), pig NPFFR2 (84% identical), rabbit NPFFR2 (81% identical), dog NPFFR2 (79% identical), mouse Npffr2 (79% identical), rat Npffr2 (78% identical), tropical clawed frog npffr2 (63% identical), zebrafish NPFFR2 (61% identical), zebrafish npffr2b (59% identical), Drosophila melanogaster SIFaR (32% identical). Paralogues in human: NPFFR1 (49% identical), HCRTR2 (30% identical), HCRTR1 (28% identical), QRFPR (26% identical), CCKAR (24% identical), GALR1 (24% identical), CCKBR (21% identical), GALR3 (20% identical), AVPR1A (18% identical), AVPR1B (18% identical), OXTR (18% identical), FFAR4 (16% identical), and 4 more.
Diseases named in the same sentence as NPFFR2 in open-access papers:
NPFFR2 is named in the same sentence as 21 diseases in open-access papers, as found by Europe PMC text mining. Sharing a sentence is not in itself a finding about the gene and the disease. The quoted sentences say what the papers report.
mastitis (9 papers, 2015 to 2024). Inflammation of breast tissue during lactation or postpartum due to an obstructed duct or infection. "Five of the genes considered the most promising candidates (i.e., BoLA-DRB3, CXCL8, GC, NPFFR2, and STAT5A) overlap with mastitis-associated QTL (CM or SCS)." (PMID 36759924, 2023). "This region includes two genes, GC and NPFFR2 that encode the vitamin D-binding protein precursor (88,695,940 to 88,739,180 bp) and the neuropeptide FF receptor 2 (89,052,210 to 89,059,348 bp), respectively, which can be involved in mastitis." (PMID 32264818, 2020). "A sequence-based association study of clinical mastitis to refine previously detected QTL regions suggested NPFFR2, SLC4A4, DCK, LIFR, and EDN3 as candidate genes for mastitis susceptibility." (PMID 27014337, 2016). "GC and NPFFR2 gene reported as candidate gene for resistance to mastitis in cattle." (PMID 38437001, 2024). "In addition, the variant on BTA6 at 87,304,531 bp is located within the NPFFR2 gene, which is a QTL for mastitis resistance, somatic cell score, milk, and protein yield." (PMID 38589805, 2024). "Additionally, two clinical mastitis candidate genes [vitamin D-binding protein precursor (GC) and neuropeptide FF receptor 2 (NPFFR2)] were detected using high-density single nucleotide polymorphic array and genomic sequencing." (PMID 31447828, 2019). "The chr6:89.04Mbp locus is adjacent two genes of note: GC and NPFFR2, the former favoured as a candidate gene for milk production and mastitis QTL in other populations, with the latter highlighted by a highly significant missense mutation as a possible causative variant in the current study." (PMID 29246110, 2017). "The comparison between these candidate QTL regions and known genes suggested that NPFFR2, SLC4A4, DCK, LIFR, and EDN3 may be considered as candidate genes for mastitis susceptibility." (PMID 26087655, 2015). "Therefore, NPFFR2, SLC4A4, DCK, LIFR, and EDN3 are candidate genes for susceptibility to mastitis." (PMID 26087655, 2015). "Furthermore, the comparison between these candidate QTL regions and known genes suggests that NPFFR2, SLC4A4, DCK, LIFR, and EDN3 may be considered as candidate genes for mastitis susceptibility." (PMID 26087655, 2015). "The NPFFR2 gene (neuropeptide FF receptor 2) along with GC and ADAMTS3 (ADAM metallopeptidase with thrombospondin type 1 motif 3) genes were reported previously to be located within a QTL region affecting clinical mastitis in Norwegian Red dairy cattle." (PMID 31311492, 2019).
Obesity (8 papers, 2012 to 2025). Accumulation of substantial excess body fat. "ATMs express NPFFR2, a receptor for the appetite-reducing neuropeptide FF (NPFF), whose plasma levels decrease in obesity, and NPFFR2 deficiency in ATMs abolished both M2 activation and ATM proliferation." (PMID 32646451, 2020). "The heritable variability of NPFFR2 is closely associated with an enhanced obesity risk; therefore, NPFFR2 plays a key role in obesity predisposition." (PMID 31447787, 2019). "In the present study, for the first time, we aimed to examine the importance of GPR10 and NPFFR2 receptors in the regulation of energy metabolism and obesity development using GPR10/NPFFR2 KO (dKO) mice." (PMID 39440369, 2024). "Collectively, our study reveals the effect of NPFF on ARC NPY neuron activity in a human-based system, indicating the potential of targeting NPFFR2 for anti-obesity therapies." (PMID 35328681, 2022). "While our data show that NPFFR2 can be targeted pharmacologically in a human-based system, the use of NPFFR2 agonists for obesity treatments may have a number of limitations." (PMID 35328681, 2022). "Additionally, such a model would allow researchers to perform studies on signaling mechanisms of NPFF to gain new insights into the nature of anorexigenic effects of NPFFR2 and to evaluate the therapeutic potential of NPFFR2 as an anti-obesity target." (PMID 35328681, 2022). "This suggests the therapeutic potential of NPFFR2 in obesity." (PMID 35328681, 2022). "Here, the authors show that neuropeptide FF receptor-2 signalling promotes thermogenesis via control of NPY expression in the arcuate nucleus, and that it absence in mice leads to a failure of activation of diet-induced thermogenesis and the development of exacerbated obesity." (PMID 30413707, 2018).
Anxiety (5 papers, 2017 to 2024). Intense feelings of nervousness, tension, or panic often arise in response to interpersonal stresses. "NPFFR2 interferes with the opioid system in the brain and its activation contributes to anxiety-like behavior in mice." (PMID 36865068, 2023). "Npffr2-shRNA-treated mice also showed a trend toward less anxiety-like behavior in the EPM (p = 0.0798, time in open arms; p = 0.065, time in closed arms, unpaired Student’s t-test)." (PMID 33202667, 2020). "Mice treated with Npffr2-shRNA also tended to show reduced anxiety-like behaviors compared to control mice." (PMID 33202667, 2020). "The NPFFR2 knockouts showed resistance to stress exposure-induced anxiety-like behaviors and HPA axis hyperactivity." (PMID 33202667, 2020). "Correspondingly, pharmacological activation of NPFFR2 directly stimulates the HPA axis through the PVN, which increases c-Fos protein expression in the PVN, causing downstream CORT secretion and anxiety-like behaviors." (PMID 33202667, 2020). "Together, our findings suggest that NPFFR2 may be a potential therapeutic target for disorders relating to stress/anxiety and HPA dysregulation." (PMID 33202667, 2020). "The findings indicate that activation of NPFFR2 induces anxiety-like behavior." (PMID 28825666, 2017). "NPFFR2 has been demonstrated to directly activate the HPA axis through the hypothalamic PVN, triggering anxiety-like behaviors." (PMID 33202667, 2020). "In this study, mice were used to evaluate the dose-response of NPFFR2 agonist-induced changes in serum CORT, c-Fos expression in PVN and anxiety-like behaviors." (PMID 28825666, 2017). "Other RFamide peptides, including neuropeptide AF, neuropeptide SF and RFamide related peptide also target NPFFR1 or NPFFR2, and have been reported to activate the HPA axis and induce anxiety- or depression-like behaviors." (PMID 28825666, 2017). "But depressive- and anxiety-like behavior were not different between WT control mice and NPFFR2 KO mice." (PMID 39440369, 2024). "The depressive- and anxiety-like behaviors were not different between WT control mice and NPFFR2 KO mice." (PMID 33202667, 2020). "The depressive- and anxiety-like behaviors were also not different between WT control mice and NPFFR2 KO mice." (PMID 33202667, 2020). "However, we did observe similar effects of PVN Npffr2 silencing on anxiety-like behaviors and HPA axis function between PVN NPFFR2 knockdown mice and congenital NPFFR2 KO mice." (PMID 33202667, 2020). "There is a growing body of evidence describing the involvement of RFamide peptides in controlling anxiety-related behaviors and HPA axis activity, but the roles for NPFFR1 and NPFFR2 remain unclear." (PMID 28825666, 2017). "On the contrary, NPFFR2 KO mice did not display anxiety-like behaviors after exposure to SPS." (PMID 33202667, 2020). "Bonferroni’s multiple comparison test reveals that SPS exposure increased the anxiety-like behaviors tested by OFT in WT mice (inner zone, p = 0.0128; outer zone, p = 0.0127), but not in NPFFR2 KO mice (inner zone, p = 0.4401; outer zone, p = 0.4408)." (PMID 33202667, 2020). "NPFFR2 deletion diminished SPS-induced HPA axis hyperactivity and GR downregulation, and it impaired negative feedback of the HPA and lessened anxiety-like behaviors." (PMID 33202667, 2020).
depression (5 papers, 2017 to 2025). "PrRP binds to the GPR10 receptor but also acts as an agonist for the neuropeptide FF receptor 2 (NPFFR2), both of which are widely distributed in brain regions associated with depression, such as the PVN and amygdala." (PMID 40362394, 2025). "Silencing of NPFFR2 expression via shRNA in the PVN inhibited the development of chronic mild stress-induced depression-like behavior in mice." (PMID 38994950, 2024). "Notably, NPFFR2 transgenic (Tg) mice are depression-prone and have an over-reactive hypothalamus-pituitary-adrenal axis." (PMID 34299230, 2021). "To test whether central neuroinflammation may act through NPFFR2 to induce depression, we used peripheral LPS treatment in this study." (PMID 34299230, 2021). "Notably, in an animal study, the activation of neuropeptide FF receptor 2 was demonstrated to potentiate inflammation-mediated depression, and thus a similar role may be hypothesized for cognitive dysfunction in post-SCI inflammation." (PMID 34804262, 2021). "We have recently reported that chronic stimulation of NPFFR2 triggers hyperactivity of the HPA axis and disrupts hippocampal feed-back regulation resulting in depression-like behaviors in mice." (PMID 28825666, 2017). "Depression-vulnerable animals show signs of insufficient PrRP signaling in the dorsolateral HTH, characterized by reduced density of PrRP-IR axons, downregulation of PrRPR and NPFFR2, and dysregulation of MCH expression in the local population." (PMID 38994950, 2024). "The expression of PrRPR and NPFFR2 was also reduced in the dorsolateral HTH of suicidal subjects, highlighting that the fine-tuning of MCH activity via PrRP may be relevant in the patomechanism of human depression as well." (PMID 38994950, 2024).
migraine (2 papers, 2020 to 2022). "Neuropeptide FF-amide peptide precursor (NPFF) is associated with migraine, and the NPFF receptor, neuropeptide FF receptor 2 (NPFFR2), has a role in the modulation of nociception." (PMID 35453627, 2022). "On the other hand, Neuropeptide FF (NPFF) is a candidate transmitter/modulator for migraine, and stimulation of its receptor, NPFFR2, increases the expression and release of CGRP in mice sensory neurons." (PMID 32640973, 2020). "Here, our findings indicated that NPFFR2 can regulate the expression of CGRP in the central sensory system, which highlights an unexplored role of NPFFR2 on the development of migraine episode." (PMID 32640973, 2020).
preeclampsia (2 papers, 2023 to 2025). Preeclampsia is a hypertensive disorder of pregnancy that is characterized by new-onset hypertension with proteinuria presenting after 20 weeks of gestation, and depending on mild or severe forms may initially present with severe headache, visual disturbances, and hyperreflexia. "Finally, the neuropeptide receptor FF 2, encoded by the gene NPFFR2, was found to be overexpressed in the placental tissue of women with preeclampsia and closely related to the production of syncytin-1 and syncytin-2 during pregnancy." (PMID 36768581, 2023). "The results of our study suggest that NPFFR2 may be associated with preeclampsia." (PMID 39926678, 2025).
Headache (1 paper, 2020). Cephalgia, or pain sensed in various parts of the head, not confined to the area of distribution of any nerve. "Here, we investigate the impact of NPFFR2 on trigeminal CGRP level in a capsaicin-induced headache mouse model." (PMID 32640973, 2020). "Our data show an important role for NPFFR2 in CGRP-evoked trigeminovascular activation, suggesting that NPFFR2-targeting therapeutics for headache may become valuable clinical tools." (PMID 32640973, 2020).
Impaired glucose tolerance (1 paper, 2024). An abnormal resistance to glucose, i.e., a reduction in the ability to maintain glucose levels in the blood stream within normal limits following oral or intravenous administration of glucose. "However, NPFFR2 KO mice exhibited impaired glucose tolerance and showed significantly greater glucose excursions in OGTT that were exacerbated by HFD." (PMID 39440369, 2024).
liver cancer (1 paper, 2022). An epithelial or non-epithelial malignant neoplasm that arises from the liver. "Here, we found that NPFFR2 is significantly up-regulated in liver cancer and its expression is related to poor prognosis." (PMID 36497331, 2022). "Silencing of NPFFR2 reduced the malignancy of liver cancer cells by decreasing cell survival, invasion, and migration, while its overexpression increased invasion, migration, and anchorage-independent cell growth." (PMID 36497331, 2022). "We discovered that neuropeptide FF receptor 2 (NPFFR2) is aberrantly expressed in liver cancer and promotes malignancy by enhancing the activity of RhoA/YAP, and inhibiting NPFFR2 dramatically reduced the malignant phenotypes." (PMID 36497331, 2022).
stress-related disorder (1 paper, 2020). Stress-related disorders are mental health disorders that are a result of an atypical response to both short and long-term anxiety due to physical, mental, or emotional stress. "Thus, NPFFR2 could serve as a potential therapeutic target for stress-related disorders." (PMID 33202667, 2020).
cancer (1 paper, 2022). A tumor composed of atypical neoplastic, often pleomorphic cells that invade other tissues. "Here, we showed that NPFFR2 is overexpressed in HCC and associated with a poor prognosis and identified that NPFFR2 is critical for tumor cell survival and aggressiveness, and these functions in cancer depend on RhoA and its downstream signaling YAP pathway." (PMID 36497331, 2022). "This is the first study to demonstrate the close association of NPFFR2 to cancer progression." (PMID 36497331, 2022). "This study presents a novel function of the RFamide peptide receptor NPFFR2 in cancer progression and suggests a potential therapeutic target for advanced HCC." (PMID 36497331, 2022). "Abnormal overexpression of NPFFR2 in some cancers, as shown in HCC tissues and cell lines, is advantageous for an anticancer target." (PMID 36497331, 2022). "To elucidate the mechanism by which NPFFR2 increases cancer malignancy, we analyzed the expression of representative downstream signaling proteins activated by GPCR signaling in NPFFR2–depleted or NPFF–treated cells." (PMID 36497331, 2022). "Depletion of NPFFR2 expression efficiently suppressed the survival, migration, and invasion of various cancer cells, and overexpression of NPFFR2 promoted migration, invasion, and anchorage-independent cell growth." (PMID 36497331, 2022). "Our in vitro results showed that inhibition of NPFFR2 was effective in preventing cancer progression through inhibition of cancer survival, migration, and invasion." (PMID 36497331, 2022). "Cytotoxicity is induced only when the expression of NPFFR2 is effectively suppressed implies that siRNA–mediated cytotoxicity is not an off–target effect and targeting NPFFR2 can selectively induce cytotoxicity in NPFFR2–overexpressing cancer cells." (PMID 36497331, 2022). "To validate the expression of NPFFR2 in cancer, we analyzed its expression in HCC patient tissues and various cancer cell lines." (PMID 36497331, 2022). "In addition, since NPFFR2 overexpression was confirmed in cancer cell lines derived from other organs, it is expected to be an effective anticancer target in other cancer types." (PMID 36497331, 2022). "Therefore, we expect NPFFR2 inhibition to have an effective cytotoxicity in cancer cells compared to normal tissues." (PMID 36497331, 2022). "Thus, for the first time, we report that NPFFR2 acts in cancer malignancy." (PMID 36497331, 2022). "The expression of NPFFR2 was also confirmed using HCC cell lines and other cancer cell lines from various origins." (PMID 36497331, 2022). "Neuropeptide FF receptor 2 (NPFFR2) is a GPCR that helps regulate pain and modulates the opioid system; however, its function remains unknown in cancers." (PMID 36497331, 2022). "Since NPFF and NPFFR2 are not mutually exclusive, there is a difference in the degree of their effect on cancer cells and in signal transduction." (PMID 36497331, 2022).
infection (1 paper, 2022). The state of being infected such as from the introduction of a foreign agent such as serum, vaccine, antigenic substance or organism. "Both transient NPFFR2 overexpression by transfection in Huh7 cells and stable NPFFR2 overexpression by lentiviral infection in SNU475 cells increased cell migration." (PMID 36497331, 2022).
tumor (1 paper, 2022). "We focused on the RhoA mechanism since this protein is commonly activated by multiple Gα proteins and promotes cell migration and invasiveness, and identified that the function of NPFFR2 on tumor progression depends on the RhoA pathway." (PMID 36497331, 2022).
NPFFR2 also shares sentences with these, for which no sentence is quoted: neurodegenerative disease (2 papers); amyotrophic lateral sclerosis (1); bacterial infection (1); diabetes (1); hepatocellular carcinoma (1); Hypertension (1); hypothyroidism (1); Parkinson disease (1).